ATM (ATM serine/threonine kinase)
Diseases named in the same sentence as ATM in open-access papers (continued):
Sharing a sentence is not in itself a finding about the gene and the disease.
cancer (continued). "Other proteins involved in DDR such as ATM, ATR, CHEK1, CHEK2, DSS1, RAD51, NBS1 and those whose deficiency causes Fanconi anaemia have been assessed in preclinical studies to determine PARP inhibitor sensitivity, with early positive results in a variety of cancer cell lines." (PMID 29069866, 2017). "Therefore, Oligo-Fucoidan supplementation promotes cancer cell death and inhibits the ATM signaling activity, an effect that may be attributable to inhibition of IL-6 activity." (PMID 28928376, 2017). "Thus, ATM inhibitors may offer a promising way to reprogram the metabolism of cancer cells to make them more vulnerable to anti-metabolic strategies." (PMID 29238697, 2017). "No variant ATM carriers were found among the other cancer cases." (PMID 27599564, 2016). "Among them RB1 or ATM have a relatively clear rational and were reported be associated with poor prognosis in other types of cancer, but genes such as FAT2 or SMARCA4 may represent novel resistance genes." (PMID 27285986, 2016). "Moreover, this information could be used to develop specific inhibitors to lock the ATM in the inactive dimer state as potential radiosensitizers for cancer radiotherapy." (PMID 27229179, 2016). "Furthermore, genotoxic stress-dependent NF-κB activation, as indicated by p65 phosphorylation and ATM phosphorylation and subsequent Bcl-XL expression were both significantly attenuated in Sam68 knockdown cancer cells." (PMID 27458801, 2016). "Besides the ability to inhibit NF-κB/STAT3, we show that GL may target cancer cell progression by the activation of ATM/ATR pathway, inducing a rapid CDC25C degradation in DU145 cells." (PMID 26683224, 2016). "Therefore, inhibiting the ATM/Chk2 signaling enhances the sensitivity of cancer cells to cisplatin." (PMID 27494891, 2016). "We conducted two meta-analyses of ATM genetic polymorphisms and cancer risk in individuals with or without radiation exposure to determine whether there was a joint effect between the ATM gene and radiation exposure in carcinogenesis." (PMID 27764772, 2016). "Although the degree of INPP4B loss that is needed for cancer cells to down-modulate ATR and BRCA1 levels and to acquire sensitivity towards PARP inhibitors still needs to be determined, we found that INPP4B loss greater than 50% in MEFs resulted in reduced levels of BRCA1, ATM and ATR proteins." (PMID 25868852, 2015). "Our data suggest that a short-term retinoic acid pulse does not downregulate ATM and therefore, would not be expected to significantly increase cancer risk by mechanisms involving ATM deficits that might occur with extended retinoic acid exposure." (PMID 28250390, 2014). "From the Catalogue Of Somatic Mutations In Cancer (COSMIC) it emerged that, from 8901 samples of all cancer types catalogued, with some tissue-dependent variations, 5% have ATM mutations and this data might underestimate the real impact of ATM aberrations in cancer." (PMID 25247188, 2014). "Conversely, ATM activation may promote cancer cell sensitivity to TRAIL." (PMID 24681585, 2014). "Accordingly, we investigated whether ionizing radiation in combination with HDAC inhibitor treatment increases the expressions of NKG2D ligands, and ATM-ATR signaling is involved in this process, and this expressional increases enhances the susceptibility of cancer cell to NK cells." (PMID 24512718, 2014).
cancer (continued). "The observation that ATM is a modulator of FLIP protein levels whose aberrant upregulation has been linked to apoptosis deregulation and to cancer therapy resistance in many tumors, provides a novel link between ATM loss of function and the acquired resistance of cancer cells to apoptosis." (PMID 24681585, 2014). "Genes in this network point to reduced HR-DNA repair as the mechanism underlying cancer susceptibility, although the precise functions of associated signalling proteins (for example PTEN, CHK2, ATM and N-terminal BRCA1) that relate to cancer development are unknown." (PMID 24286369, 2013). "The deregulation of these biological functions in non-cancerous cells suggests the loss of ATM, with associated changes in miRNA expression levels, may predispose or drive the early stages of cancer formation." (PMID 23741392, 2013). "Therefore, though our in vitro data clearly demonstrated the suppression of ATM by miR-18a sensitized cancer cells to etoposide, the role of ATM role on chemo-resistance may vary in a chemotherapeutic-specific and tumor-specific manner in vivo." (PMID 23437304, 2013). "Furthermore, our results suggest that ATM agonists could be used as anti-cancer agents, in part by accelerating Mdm2 destruction." (PMID 22976441, 2012). "ATM interactions for synthetic lethality could lead to targeted therapy for appropriate cancers." (PMID 22350747, 2012). "Therefore, upregulated ATR activity in COX-2 overexpressing cancer cells may compensate for the ATM activity inhibited by gefitinib, and thereby prevent MC." (PMID 20731837, 2010). "Moreover, ATM is frequently inactivated in sporadic cancers, particularly lymphoid malignancies." (PMID 19674456, 2009). "Defining the nature and temporal sequence of molecular events that are disrupted by CS through activation and eventual dysregulation of normal defense mechanisms such as ATM and its downstream effectors may allow a more precise understanding of how CS promotes cancer development." (PMID 17594478, 2007). "These early results suggest that screening for ATM mutations in cancer patients may not be of value in predicting adverse reactions." (PMID 9413938, 1997). "We further extended this framework to five additional cancer-related genes (VHL, ATM, BRCA1, RAD51C, and BAP1), establishing a generalizable framework for gene-specific VEP with potential applications in precision medicine." (PMID 41955512, 2026). "In this study we review the ATM/Chk2 and ATR/Chk1 axes in cancer and the new drugs developed to inhibit these proteins, which are being tested in different phases of preclinical experimentation or clinical trials." (PMID 40422251, 2025). "It further proves the effectiveness of the combination of ATM inhibitors with radiotherapy and ICB therapies, providing a new strategy for enhancing the efficacy of cancer treatment." (PMID 40825766, 2025). "Based on the International Cancer of the Pancreas Screening Consortium (CAPS) consensus criteria, carriers with a family history of PC may be eligible for high-risk surveillance (such as Magnetic Resonance Imaging (MRI) or EUS if a pathogenic germline ATM variation is found." (PMID 41374970, 2025).
cancer (continued). "DNA sensors ATM and ATR are both involved in detecting these lesions, initiating DDR pathways responsible for subsequent DNA repair and promoting cancer cell survival." (PMID 40514666, 2025). "Enriched terms such as lysosome organization and chromosome segregation support cancer cell survival and genomic stability, while pathways like PI3K/Akt/mTOR and ATM signaling promote tumor growth and DNA repair." (PMID 40748325, 2025). "In this study, we demonstrated that FAM111B expression correlates with 17 HR repair proteins, including ATM, ATR, and BRCA1/2, in 30 out of 33 of the studied cancers." (PMID 40243892, 2025). "Numerous studies have elucidated the pivotal roles of ATM and BRCA1/2 genes in cancer progression, therapeutic resistance, and immune modulation, highlighting their potential as therapeutic targets across diverse malignancies." (PMID 40256842, 2025). "Simultaneous inhibition of ATM and ATR has been shown to induce cancer cell death through synthetic lethality in preclinical models." (PMID 40875525, 2025). "Inhibiting hyperactive or synthetically lethal DDR components (e.g., PARP, ATM, ATR, DNA-PK, Wee1) in cancer cells can impair the repair of radiation-induced DNA damage, particularly double-strand breaks (DSB), thereby achieving targeted radiosensitization." (PMID 41189946, 2025). "Paradoxically, ATM can also phosphorylate SIRT7 following anti-cancer drug treatment, inhibiting specific DNA repair pathways and promoting cancer cell survival." (PMID 41471367, 2025). "These pathways intersect at critical nodes of cancer biology: TGF-β promotes EMT and immunosuppression; ATM coordinates genomic stability; and Hippo signaling modulates organ size and tumor growth." (PMID 41301482, 2025). "ATM inhibitors are specifically designed to disrupt the DNA damage response (DDR), impairing DNA repair mechanisms in cancer cells and inducing tumour cell death." (PMID 40256842, 2025). "In PDAC cancer cell lines, we evaluated the abundances of TOPBP1, p-ATR, p-ATM, p-CHK1, and p-CHK2 proteins—key genes in the ATR and ATM pathways." (PMID 39920847, 2025). "Several small-molecule inhibitors targeting ATM/Chk2 or ATR/Chk1 are currently being tested in preclinical and/or clinical settings, showing promise in cancer models and patients." (PMID 40422251, 2025). "Radiosensitization, induced by inhibiting ATM, ATR or DNA-PKcs, has been demonstrated in many cancer types." (PMID 40332379, 2025). "We propose the underlying mechanism that RBM17 promotes CHEK1 protein expression in the ATM/ATR pathway, triggering the development of chemoresistance in cancer cells." (PMID 40243905, 2025). "This review discusses the roles of three major kinases ATM, ATR, and DNA-PK in sensing DNA damage and catalysing DNA repair, as well as their involvement in cancer." (PMID 40256842, 2025). "For tumors with low SLFN11 expression, systematically evaluate the efficacy of the combination regimens of ATR inhibitors, ATM inhibitors, CHK1 inhibitors, and WEE1 inhibitors with standard chemotherapy in different cancers." (PMID 40766331, 2025). "In self-identified White patients, PGV rates in ATM, BRCA1, BRCA2, CHEK2 and Lynch genes were significantly higher compared to two cancer-free male cohorts." (PMID 40832411, 2025). "When DSBs occur due to radiation or other insults, ATM activation induces an effective DNA damage response (DDR), making it a critical factor in cancer cell resistance to radiation." (PMID 41190241, 2025).
cancer (continued). "ATM and ATR are induced in cancer cells exposed to chemotherapy and blocking them is proposed as an attractive strategy to overcome resistance in cancer patients." (PMID 38366255, 2024). "While numerous studies have already examined the effectiveness of ATM and ATR inhibition alone or in combination with RT for different cancer types, there remains a notable gap in directly comparing their impact on the immunogenicity of HNSCC cells." (PMID 39411143, 2024). "Among these were genes with putative tumor suppressor function in different cancer types including FOXP1, STK4,ATM, and others." (PMID 38464090, 2024). "In addition, parkin (PARK2), ataxia telangiectasia mutated (ATM), phosphatase and tensin homolog deleted on chromosome 10 (PTEN), and receptor-type tyrosine-protein phosphatase delta (PTPRD) have been demonstrated to be critical targets in the development of cancers and neurodegenerative diseases." (PMID 38592583, 2024). "Our study revealed the role of the ATM-CBP-DOT1L axis in MLLr-AML and broadened the view of DDR enzymes as potent targets for cancer therapy." (PMID 38671157, 2024). "We also found that 5-FU-treated RER-positive HCT116 cancer cells (at pHe 7.4) exhibited a dose-dependent increase in phosphorylated ATM, ATR, CHK1, and CHK2, reaching levels observed in untreated acid-exposed cancer cells (pHe 6.5)." (PMID 38366255, 2024). "Their capacity to specifically attach to and possibly regulate the activity of proteins such as ATM, ATR, CHK1, and WEE1 reveals a pathway towards novel treatment approaches, emphasizing the essential role of DDR in the survival and growth of cancer cells." (PMID 38961104, 2024). "These marker genes play diverse roles in cancer, such as promoting growth and proliferation (MYC, HIF1A, ATM), inhibiting apoptosis (MCL1, BIRC3, BCL2) and facilitating invasion (CXCR4, CD55)." (PMID 38982317, 2024). "Both ATM and ATR DDR pathways are being targeted in clinical trials for diseases such as cancer, which highlights the significance of basic mechanistic studies on how ATM and ATR are activated to maintain genome stability." (PMID 39112456, 2024). "Apart from ERK and ATM kinases, PI3K can participate in cancer development by promoting Sp1 phosphorylation." (PMID 39228402, 2024). "In this paper, we examine data from a large cohort study to derive relative and absolute risks for all cancer types, for carriers of PTVs and rMSVs in CHEK2 and ATM." (PMID 39209703, 2024). "A similar pattern of ATM, ATR, and checkpoint kinase activation was observed in 5-FU-treated RER-negative HT-29 cancer cells at pHe 7.4 vs. untreated HT-29 cells at pHe 6.5." (PMID 38366255, 2024). "Drugs targeting ATM and ATR preferentially inhibit growth of acid-exposed cancer cells and sensitize them to chemotherapy." (PMID 38366255, 2024). "Essential proteins frequently overexpressed in cancer cells include PARP, DNA-PKcs, BRCA1/2, ATM, ATR, and Chk1/2." (PMID 39372203, 2024). "To further support the activation of ATM and ATR pathways under acidosis, we examined them in cancer cells exposed to genotoxic 5-fluorouracil (5-FU)." (PMID 38366255, 2024). "Following irradiation, a caspase-independent wave of CAD activation was observed in cancer cells, which depended on the phosphorylation of ICAD by ATM/ATR." (PMID 38977850, 2024).
cancer (continued). "In vitro study suggested that 6-G possesses anti-cancer activity by inducing cell apoptosis in human PCa PC-3 cells by affecting AR regulated DDR genes (BRCA1, BRCA2, and ATM ) which is involved in cell survival." (PMID 38166796, 2024). "Induction of genomic instability to facilitate cancer cell death is also the strategy employed by AZD1390 (AstraZeneca), a small molecule inhibitor of ATM." (PMID 39095874, 2024). "The distribution patterns of several known cancer driver genes, including CTNNB1, ATM, CHEK2, and NCOR1, exhibit racial disparities across datasets." (PMID 39541191, 2024). "Key molecules, including PARP, ATM/ATR, amplified/overexpressed transcription factors, and DNA methyltransferases, maintain the cancer genome and keep abnormal DNA replication and cell division operating, while escaping critical DNA damage and cell death." (PMID 37514113, 2023). "In this review, we introduce the activation of the PI3K/AKT/mTOR signalling pathway in cancer and the mechanisms by which PIKK members ATM, ATR, and DNA-PK repair DNA damage." (PMID 37489050, 2023). "PIKK members ATM, ATR, and DNA-PK are closely related to DNA damage repair and have complex effects on cancer progression and treatment." (PMID 37489050, 2023). "Taken together, these results indicate that M3541 inhibited ATM functions in both DSB repair and cell cycle checkpoint control in irradiated cancer cells and modified ATM-dependent checkpoint response by shifting cell cycle arrest to predominantly G2/M." (PMID 36656721, 2023). "The inhibitors of DDR have been extensively developed, including ATM, ATR, and DNA-dependent protein kinase (DNA-PK) to deal with cancer cells." (PMID 36794257, 2023). "At the same time, in a large-scale study of BC women aged 35–59 years, who were mainly of Northern and Western European descent, PVs in CHEK2, ATM, PALB2, and PMS2 genes were the most frequent among the 25 cancer genes tested, after PVs in BRCA1/2." (PMID 37791908, 2023). "Since homologous recombination is an essential DNA repair pathway to preserve genomic stability, its inhibition, namely, by targeting ATM, ATR, CHK1, CHK2, WEE1, RAD51 and RAD52, represents a promising therapeutic strategy in cancer treatment." (PMID 38136266, 2023). "As healthy cells do not have the same restricted DNA repair capacity typically found in cancer cells, we suggested that healthy cells—fibroblasts in our model system—should adapt better to inhibition of DDR, while targeting ATR or ATM with specific inhibitors." (PMID 36229655, 2023). "HMGA2 not only binds ATM, but is an ATM substrate upon DNA damage, suggesting that HMGA2 functions in DSB signaling and repair upon genotoxic stress in cancer cells." (PMID 36980621, 2023). "Consistent with this, herein, we show that inhibition of ATM induces the activation of cGAS-STING-IFNβ ubiquitously in multiple human and murine cancer cell lines." (PMID 36778120, 2023). "Together, these results demonstrated that ATM inhibition leads to cGAS-STING activation and IFNβ signaling in multiple cancer types." (PMID 36778120, 2023). "A paralog of SERPINE1, SERPINE2, has been recently reported to participate in DNA repair process through the direct interaction with ATM and MRE11 to protect cancer cells from IR-induced DNA damage." (PMID 36681663, 2023). "The most common genes in which PPGVs were identified pan-cancer were BRCA2 (16.9% of PPGVs), MUTYH (15.0%), ATM (13.4%), CHEK2 (11.7%), and BRCA1 (9.8%)." (PMID 37568048, 2023). "Since ATM and ATR are the first molecules activated after DNA damage, their dual inhibition with Top2 inhibitors made them a potential combination therapy for cancer proliferation arrest and apoptosis." (PMID 36678591, 2023).